LY6K (lymphocyte antigen 6 family member K)
Description:
Required for sperm migration into the oviduct and male fertility by controlling binding of sperm to zona pellucida (By similarity). May play a role in cell growth.
Synonyms: Ly-6K; HSJ001348; FLJ35226; CT97; URLC10
Tractability: Antibody: UniProt places it where antibodies can reach, with high confidence; its Gene Ontology location is reachable by antibodies, with high confidence; UniProt predicts a signal peptide or a membrane-spanning region. PROTAC: ubiquitination databases record sites on it; a small molecule that binds it is known.
Gene: Protein-coding gene on chromosome 8 (142,700,111 to 142,705,127, forward strand). Ensembl gene ENSG00000160886.
Subcellular location: Secreted; Cytoplasm; Cell membrane; Cytoplasmic vesicle, secretory vesicle, acrosome; Membrane raft
Subcellular location (Human Protein Atlas): Acrosome; Mid piece; Plasma membrane; Actin filaments; Equatorial segment; Nucleoplasm; Predicted to be secreted
Pathways (Reactome):
Metabolism of proteins: Post-translational modification: synthesis of GPI-anchored proteins
Gene Ontology:
Biological process: binding of sperm to zona pellucida
Cellular component: cytoplasm; extracellular region; acrosomal vesicle; membrane raft; plasma membrane
Genetic constraint (gnomAD): Loss-of-function variants: 6 observed, 5.42 expected, observed/expected ratio (o/e) 1.11, 90% interval 0.59 to 1.84. That is too few expected variants to judge how well the gene tolerates losing a copy. Missense variants: 200 observed, 192.52 expected, observed/expected ratio (o/e) 1.04, 90% interval 0.93 to 1.17. Synonymous variants: 95 observed, 76.41 expected, observed/expected ratio (o/e) 1.24, 90% interval 1.05 to 1.47.
Homologues: Orthologues: chimpanzee LY6K (95% identical), macaque LY6K (84% identical), mouse Ly6k (35% identical), rat Ly6k (35% identical). Paralogues in human: GML (27% identical).
Diseases named in the same sentence as LY6K in open-access papers:
LY6K is named in the same sentence as 37 diseases in open-access papers, as found by Europe PMC text mining. Sharing a sentence is not in itself a finding about the gene and the disease. The quoted sentences say what the papers report.
bladder cancer (13 papers, 2011 to 2023). "In particular, LY6K has been implicated in cell growth, migration, and invasion in bladder cancer cell lines, and its increased expression has been associated with reduced five-year overall survival in bladder cancer patients." (PMID 33213418, 2020). "A robust link between rs2294008 and risk of bladder cancer through cg24023258 may identify LY6K expression as a serum biomarker of bladder cancer susceptibility in non-smokers." (PMID 33213418, 2020). "Lymphocyte antigen 6 complex locus K (LY6K) was considered as a molecular target to treat bladder cancer." (PMID 36193203, 2022). "ASPH has been reported as a potential therapeutic target for malignant glioma (PMID: 27981247), and LY6K is a novel bladder cancer molecular target that integrated genome-wide analysis (PMID: 21063397)." (PMID 31608231, 2019). "We found that Ly6K mRNA expression was significantly increased in 188 samples of bladder cancer than 68 samples of normal relevant tissue in Lee studies." (PMID 26862846, 2016). "The gene expression analysis showed that bladder cancer expresses significant high levels of Ly6D, Ly6E, Ly6K." (PMID 26862846, 2016). "Some antigens of CTAs family have also been proved to be novel biomarkers for various types of malignancies, such as MAGE-1 for differentiated advanced gastric cancer, LY6K for bladder cancer, and sperm protein 17 for cervical cancer." (PMID 24799889, 2014). "Cell viability assays demonstrated that the significant inhibition of cell growth, migration and invasion occurred in LY6K-knockdown bladder cancer cell lines." (PMID 24137407, 2013). "LY6K was found to be a molecular marker for non-small-cell lung carcinoma, head-and-neck squamous cell carcinoma, breast cancer, bladder cancer, and esophageal squamous cell carcinoma." (PMID 37655157, 2023). "LY6K: Increased expression of LY6K has also been reported in metastatic ER positive breast cancer, esophageal squamous cancer, gingivobuccal cancers, bladder cancer, and lung cancer." (PMID 31068932, 2019). "Interestingly, LY6K from clinical data demonstrated that overexpression of LY6K leads to a few organ cancers, including breast cancer, esophageal squamous cancer, gingivobuccal cancers, bladder cancer, and lung cancer." (PMID 33552125, 2020). "LY6K and LY6D are consistently upregulated across many cancers and show increased expression in bladder cancer." (PMID 33213418, 2020).
breast carcinoma (13 papers, 2011 to 2024). "We, for the first time, found miRNAs involved in the regulatory molecular mechanism between ERα and LY6K and related to tamoxifen susceptibility in breast cancer." (PMID 27304060, 2016). "By investigating the molecular mechanism behind the functions of miR-192-5p and miR-500a-3p in the regulation of ERα and LY6K, how miR-192-5p, induced by LY6K, causes tamoxifen resistance by inhibiting ERα expression in ERα-positive breast cancer." (PMID 27304060, 2016). "In this report, we investigated the relationship between chromatin modifications and their association with DNA methylation patterns and LY6K expression in breast carcinoma and cell lines." (PMID 27494879, 2016). "First, we found that LY6K expression was significantly correlated with overall survival (OS) and distant metastasis, while DNA methylation was inversely associated with LY6K expression in breast cancer cell lines and tumors." (PMID 27494879, 2016). "Additionally, the same study found that LY6K promotes gene signatures associated with drug resistance in breast cancer, emphasizing its role in immune evasion and therapy resistance." (PMID 39727968, 2024). "LY6E, together with LY6K, has also been implicated in breast cancer proliferation by altering TGFβ-dependent breast cancer cell physiology, resulting in increased immune checkpoint molecules PD-L1 and CTLA4 in tumor-infiltrating T regulatory cells yet decreased natural killer (NK) cell activation." (PMID 31684192, 2019). "Interestingly, LY6K expression was lower in the SNP242 mutation which creates de novo PAX3 transcription factor binding sites in breast cancer cell lines." (PMID 27494879, 2016). "The invasiveness and metastatic function of LY6K in cancer as a diagnostic biomarker and therapeutic target has been elucidated in various cancers such as head and neck squamous cell carcinoma, breast cancer, lung and esophageal carcinomas, bladder cancer, and esophageal squamous cell carcinoma." (PMID 27494879, 2016). "In addition, LY6K methylation might be an independent prognostic marker in breast carcinoma and may be useful for selecting patients with higher risk of recurrence, death, and metastasis and for chemotherapy response." (PMID 27494879, 2016). "Finally, this study proposes understanding of epigenetic changes in LY6K may contribute to the diagnosis of cancer risk and prognosis of patients with breast cancer." (PMID 27494879, 2016). "High expression of LY6K at mRNA level is reported to be related to poor survival outcomes in various cancers, including breast cancer, cervical cancer, and colorectal cancer." (PMID 34980214, 2022). "The highest LY6K expression was seen in cervical, head and neck, bladder, esophageal, and breast cancer." (PMID 32098321, 2020). "The role of lymphocyte antigen 6 complex, locus K (LY6K) in breast cancer has been studied, whereas the epigenetic control of LY6K transcription is not fully understood." (PMID 27494879, 2016). "High Ly6K mRNA expression in breast cancer was significantly correlated with decreased three-year overall survival (dead, n=31 vs alive, n=295) and one-year overall survival (dead, n=3 vs alive n=156) in Kao and Pawitan studies." (PMID 26862846, 2016). "We have shown that LY6K and ERα have an inverse correlation in breast cancer and that miRNAs involved in this mechanism affect tamoxifen resistance." (PMID 27304060, 2016). "To confirm the inverse correlation between ERα and LY6K, we observed ERα expression by overexpressing LY6K in ERα-positive breast cancer cell lines." (PMID 27304060, 2016). "We have tested for human Ly6E and Ly6K in breast cancer and delineated the molecular mechanism behind cancer cell growth, metastasis and drug resistance (being published separately)." (PMID 26862846, 2016). "Nonetheless, there are few studies to supporting the effect of LY6K on various type of breast cancer." (PMID 27304060, 2016).
breast carcinoma (continued). "We found that PAX3 binding sites, created by SNP242, differentially increase LY6K promoter methylation, which in turn influences migration of breast cancer cells." (PMID 27494879, 2016). "High Ly6K mRNA expression in breast cancer was significantly correlated with poor five-year overall survival (low Ly6K, n=51; high Ly6K, n=52; HR=1.25, p=0.021, HR=hazard ratio, n=number of patients) shown by PROGgeneV2." (PMID 26862846, 2016). "When we further analyzed this set of clinical samples, we found that LY6K-positive breast cancer tissues presented a lower E-cadherin, an epithelial marker, expression level, but E-cadherin expression increased in LY6K-negative breast tumor samples." (PMID 27494879, 2016). "We transiently and stably knocked down LY6K in the LY6K-positive breast cancer cell lines, MCF7-ADR and mouse adapted MDA-MB-231 cells (MB-231/A), using siRNA and lentivirus, respectively." (PMID 27494879, 2016). "In this study, we found that lymphocyte antigen 6 complex (LY6K), which is a member of the Ly-6/μPAR superfamily and related to breast cancer progression and metastasis, is inversely correlated with ERα expression." (PMID 27304060, 2016). "To investigate LY6K is involved in the regulation of ERα expression, we evaluated both the mRNA and protein levels in the breast cancer cell lines." (PMID 27304060, 2016). "Here, we report that breast cancer patients with increased LY6K expression had shorter disease-free and overall survival than the patients with low levels of LY6K by multivariate analysis." (PMID 27494879, 2016). "In this study, we found an inverse correlation between the expression of ERα and LY6K in breast cancer." (PMID 27304060, 2016). "Recently, LY6K was reported to be a molecular biomarker in breast cancer, bladder cancer and esophageal squamous cell carcinomas." (PMID 27304060, 2016). "In our data, we clearly found that the expression of LY6K and ERα is negatively correlated in breast cancer cells." (PMID 27304060, 2016). "Ly6K mRNA expression was significantly increased in 497 samples of breast cancer than 205 samples of normal tissue in TCGA (Unpublished, NCI) and Curtis study." (PMID 26862846, 2016). "To validate the miRNA microarray analysis, we explored the possibility that selected miRNAs were activated by transient overexpression of LY6K or ERα in each breast cancer cell." (PMID 27304060, 2016). "In conclusion, we showed for the first time that the involvement of miR-192-5p and miR-500a-3p regulates the mechanism for the interaction between ERα and LY6K and is related to tamoxifen responsiveness in breast cancer." (PMID 27304060, 2016). "It was reported that highly upregulated LY6K is related to cell proliferation and metastatic abilities in breast cancer." (PMID 27304060, 2016). "We investigated the relationship between the expression of these EMT-related markers and LY6K in breast cancer cell lines." (PMID 27494879, 2016). "Several groups have shown elevated expression of LY6K mRNA in human head and neck squamous cell carcinomas and in lung, oesophageal, and breast cancers." (PMID 21063397, 2011). "LY6A is aberrant expressed in pituitary tumors and can be a tumor-initiating biomarker of lung cancer; LY6E can serve as an independent prognostic factor for CC and is closely associated with the migration and invasion of CC; and LY6K promotes the progression of bladder, ovarian, and breast cancers." (PMID 38067506, 2023). "High expression of LY6K promotes the progression of bladder, ovarian, and breast cancer." (PMID 38067506, 2023). "Lymphocyte antigen 6K (LY6K), a cancer-testis protein, is highly expressed in 70% of clinical cases of triple-negative breast cancer and the expression of LY6K is associated with poor survival outcome in breast cancers." (PMID 36900259, 2023).
breast carcinoma (continued). "To test whether NSC243928, a binder of LY6K, may reduce in vivo tumor growth, we selected two immune-competent syngeneic mammary tumor models, 4T1 and E0771, both models that are well used in immuno-oncology drug development." (PMID 36900259, 2023). "LY6K is upregulated in breast cancer tissues compared with NTL expression." (PMID 27494879, 2016). "In addition, LY6K expression is regulated by the AP-1 transcription factor that promotes cell proliferation, invasive and metastatic abilities in breast cancer cells." (PMID 27304060, 2016). "Taken together, breast cancer risk and metastasis were significantly associated with not only LY6K expression, but also methylation of CGI shore which induced by SNP242 mutation." (PMID 27494879, 2016). "Higher Ly6K expression was correlated with breast cancer stage as seen by the significant higher expression of Ly6K in ductal stage N1+ (n=19) than ductal stage N0 (n=20) and invasive stage N1+ (n=9) than invasive stage N0 n=22) in Julka, and Stickeler studies." (PMID 26862846, 2016). "Having demonstrated the miRNA-dependent reciprocal regulation of LY6K and ERα expression, we further studied whether miR-192-5p and miR-500a-3p are functionally involved in tamoxifen responsiveness in breast cancer." (PMID 27304060, 2016). "Taken together, epigenetic alterations, particularly DNA methylation of the LY6K CGI shore and CGI, may contribute to LY6K activation in breast cancer." (PMID 27494879, 2016). "Finally, we compared LY6K expression levels and methylation status in breast cancer subtypes using the public datasets obtained from cBioPortal TCGA database (mRNA microarray and methylation array HM27)." (PMID 27494879, 2016). "LY6K methylation was analyzed by MCA in 30 breast carcinomas and 15 NTL breast tissues." (PMID 27494879, 2016). "The migration activity was significantly higher in LY6K-transfected breast cancer cell lines." (PMID 21063397, 2011). "Finally, we observed an inverse correlation between LY6K and ERα in primary breast cancer samples." (PMID 27304060, 2016). "To further ascertain whether miRNAs involved in the mechanism for LY6K and ERα are correlated with clinical outcomes in breast cancer patients, we first investigated the inverse correlation between LY6K and ERα expression in breast primary tumor samples obtained from oncomineTM." (PMID 27304060, 2016). "The activation of TGF‐β and EGF signaling pathways plays a critical role in cancer metastasis and proliferation, respectively, where LY6K is required for TGF‐β‐ and EGF‐induced metastasis in breast cancer and glioblastoma." (PMID 37076981, 2023). "To confirm the effect of NSC243928 in LY6K-expressing cells, we observed the parental control and sh2 LY6K knockdown in MDA-MB-231 cells, a triple negative breast cancer cell line." (PMID 32098321, 2020). "In conclusion, our findings show that LY6K is frequently activated by CGI shore hypomethylation and active histone marks in breast carcinomas." (PMID 27494879, 2016). "Seven of the 12 human breast carcinoma cell lines (58%), MCF7-ADR, MDA-MB-157, MDA-MB-231, MDA-MB-435, MDA-MB-436, MDA-MB-468 and SK-BR-3 lines expressed the highest level of LY6K mRNA." (PMID 27494879, 2016). "Additionally, LY6K has been shown to promote invasion and metastasis by upregulating matrix metalloproteinase proteins (MMP-2 and MMP-9) in breast cancer." (PMID 39727968, 2024). "The expression of miR-500a-3p is also up-regulated by ERα overexpression in LY6K-positive and ERα-negative breast cancer." (PMID 27304060, 2016). "Ly6K mRNA expression was significantly higher in triple negative breast cancer (TNBC) (n=163) than non-TNBC breast cancer (n=584) in Bittner (Unpublished, GSE2109), Korde, TCGA (Unpublished, NCI), Julka, Zhao, Richardson2 and Miyake studies." (PMID 26862846, 2016). "The results together indicate that miR-500a-3p, induced by ERα, regulates tamoxifen sensitivity by targeting LY6K in ERα-negative breast cancer cells." (PMID 27304060, 2016).
breast carcinoma (continued). "Ectopic expression of ERα led to the reduction of both LY6K mRNA and protein expression in ERα-negative breast cancer cells." (PMID 27304060, 2016). "LY6K also was upregulated in breast cancer patients with distant metastases than those without distant metastases, downregulating E-cadherin expression." (PMID 27494879, 2016). "Here, we found that LY6K downregulates the expression of E-cadherin in breast cancer cells, carcinomas and xenograft mice, whereas does not increase vimentin." (PMID 27494879, 2016). "Furthermore, we determined that elevated ERα stimulates miR-500a-3p and suppress LY6K expression in ERα-negative breast cancer cells." (PMID 27304060, 2016). "In addition, re-expression of ERα in ERα-negative breast cancer cells increased miR-500a-3p expression and directly inhibits LY6K expression." (PMID 27304060, 2016). "Some breast carcinomas and cell lines expressed LY6K, but others did not." (PMID 27494879, 2016). "Furthermore, LY6K localizes at the plasma membrane as a GPI‐anchored protein and affects various cellular functions, including cell differentiation, proliferation, migration, adhesion, and invasion in lung adenocarcinoma, esophageal cell carcinoma, breast cancer, and cervical cancer." (PMID 37076981, 2023). "Similarly, our results suggested a novel mechanism involving the downregulation of LY6K via the miR-500a-3p axis, induced by ERα, and may be involved in attenuating metastatic and proliferate capacities in ERα-negative breast cancer." (PMID 27304060, 2016). "In addition, we observed that the expression of LY6K was reduced by ectopic expression of ERα in MCF7-ADR and MDA-MB-468, well known as ERα-negative breast cancer cells." (PMID 27304060, 2016). "We confirmed that the ERα-positive breast cancer cell lines, MCF7 and T47D, did not express LY6K mRNA and protein, whereas the ERα-negative breast cancer cell lines, MCF7-ADR and MDA-MB-468, expressed LY6K mRNA and protein." (PMID 27304060, 2016).
esophageal cancer (13 papers, 2011 to 2024). A primary or metastatic malignant neoplasm involving the esophagus. "LY6K is especially of interest as high mRNA expression of this gene is associated with poor patient survival in thyroid, kidney, uterine, and esophageal carcinomas." (PMID 37141412, 2023). "Ly6K mRNA expression was significantly increased in 51 samples of esophageal cancer than 51 samples of normal tissue in Su study." (PMID 26862846, 2016). "The suppression of LY6K expression with siRNA effectively inhibited the growth of LY6K-expressing lung and esophageal cancer cells." (PMID 26568964, 2015). "A new immunotherapy using established cytotoxic T lymphocyte targeting LY6K was studied in lung and oesophageal cancer cell lines, meaning that LY6K is a promising target for BC immunotherapy." (PMID 21063397, 2011). "Several investigations found overexpression of LY6K in several human malignancies, such as head and neck squamous cell carcinomas and breast, lung, and oesophageal cancers." (PMID 21063397, 2011). "This gene codes for lymphocyte antigen 6 family member K, which may be involved in the regulation of cell growth, as it was demonstrated that silencing of LY6K expression by siRNA resulted in growth suppression of lung and esophagus cancer cells." (PMID 32054071, 2020). "In advanced oesophageal cancer, IMP3 and other peptides (TTK, LY6K) have been used therapeutically as vaccines in phase II clinical trials." (PMID 37627115, 2023).